CD38 (CD38 molecule)
Diseases named in the same sentence as CD38 in open-access papers (continued):
Sharing a sentence is not in itself a finding about the gene and the disease.
tumor (continued). "It binds to CD38 on MM cells, exerts its ectoenzyme hydrolytic activity to generate metabolites that regulate intracellular calcium levels and activate purinergic receptors, thereby leading to cell lysis and immune-mediated tumor suppression." (PMID 40529366, 2025). "Notably, across all tumor types assessed, CD38-expressing Tregs were significantly enriched at tumor sites compared to those at the spleen and DLN." (PMID 40117361, 2025). "To assess whether this elevated CD38 expression in tumor cells conferred any therapeutic benefits, we conducted a combination therapy study involving αCD38 antibody and panobinostat using our mouse model of CTCL." (PMID 40057636, 2025). "Importantly, when we collected bone marrow from these mice at the end of the study and stained the cells for human CD45+ and human CD38+ for flow cytometry analysis, the CTCL tumor cells had maintained their respective CD38+ and CD38- expression statuses." (PMID 40057636, 2025). "Isatuximab is a distinct anti-CD38 monoclonal antibody that binds a unique epitope and is reported to induce tumor cell death through multiple mechanisms, including direct apoptosis, antibody-dependent cellular cytotoxicity, phagocytosis, and inhibition of CD38 enzymatic activity." (PMID 41228289, 2025). "These contradictory findings highlight the complex role of CD38 in cancer metabolism and immunomodulation, though its precise function in the tumor microenvironment remains unclear." (PMID 40529366, 2025). "Further investigation is required to gain a deeper understanding of the infiltrating immune populations in CHS that express and utilize CD38, their interactions with tumor cells, and the potential targeting of these cells and molecules for the effective elimination of CHS." (PMID 40382743, 2025). "Notably, EVsMNs and CD38‐EVsMNs groups showed significantly better tumour site delivery than EVsi.v and CD38‐EVsi.v groups at 1 and 3 h post‐administration." (PMID 40317915, 2025). "Importantly, CD38‐EVs exhibited substantially reduced uptake by non‐tumour stromal cells than standard EVs, demonstrating their potential safety for delivering chemotherapeutic agents by targeting tumour cells and sparing non‐tumour cells." (PMID 40317915, 2025). "Daratumumab, the first antibody targeting CD38, has demonstrated sustained anti-tumor responses in clinical settings through mechanisms including antibody-dependent cell-mediated cytotoxicity, antibody-dependent cellular phagocytosis, and complement-dependent cytotoxicity." (PMID 40382743, 2025). "At the relapse, tumor plasma cells maintain CD38 expression, and retreatment with daratumumab could be the logical choice, especially if other treatment options are unavailable." (PMID 39857790, 2025). "Similarly to our CD38-BARs, the CD38-specific BiCE mediated a strong CDC against CD38-expressing tumor cells." (PMID 41254160, 2025). "Because of the technical challenges in retrieving sufficient CD38+ Tregs from the tumor site for functional studies, we first checked whether in vitro–differentiated Tregs (iTregs) also expressed CD38." (PMID 40117361, 2025). "Similarly, BITE therapies targeting CD38/CD3, such as AMG 424, have shown strong MM cell eradication but carry a risk of ‘off-tumor’ T-cell cytotoxicity, potentially impacting normal B, T, and NK cells." (PMID 39806405, 2025). "Gene-editing technologies (e.g., CRISPR/Cas9) have markedly augmented CAR-NK cell function, for instance, through knockout of inhibitory receptors (e.g., CISH, TGF-βR2) or metabolism-related genes (e.g., CD38), thereby improving both anti-tumor activity and adaptability to the TME." (PMID 41488873, 2025). "In this study, we sought to discern the mechanistic impact of tumor-directed versus immune-directed effects of a CD38-targeted AttenukineTM, leveraging different immunocompromised and immunocompetent mouse models and various human or mouse CD38-directed AttenukineTM." (PMID 40315226, 2025).
tumor (continued). "Additional qPCR analysis of tumor cells from the mouse bone marrow revealed a significant increase in relative CD38 expression in the panobinostat treatment groups compared to αCD38 antibody alone, highlighting the impact of panobinostat on enhancing CD38 gene expression in vivo." (PMID 40057636, 2025). "Moreover, MDSCs with elevated CD38 expression possess a greater capacity to suppress activated T cells and promote tumor growth compared to those with lower CD38 expression." (PMID 40134607, 2025). "This monoclonal antibody has demonstrated its killing activity against CD38-expressing tumor cells, inducing antibody dependent cellular cytotoxicity (ADCC), complement–dependent cytotoxicity (CDC), macrophage-mediated phagocytosis and cell lysis in CD38+ myeloid derived suppressor cells and Tregs." (PMID 40005960, 2025). "CD38 is increasingly emerging as a potential target for anti-tumor therapies." (PMID 39996780, 2025). "Interestingly, after 21 days, the EVs‐DoxMNs group showed an increased tumour proliferation rate, whereas the CD38‐EVs‐DoxMNs group exhibited a slower tumour expansion rate." (PMID 40317915, 2025). "The presence of a differential intratumoral pharmacodynamic response in a subset of patients with elevated CD38+ cells highlights that tumor-intrinsic factors may play a role in the activity of modakafusp alfa in solid tumors." (PMID 41445795, 2025). "Additionally, CD38 inhibition has been shown to enhance the anti-tumor function of chimeric antigen receptor (CAR) T cells, suggesting its role in T cell dysfunction." (PMID 41488275, 2025). "Tumor cells were positive for CD38, CD138, CD22, CD79a, MUM1, CD45, and kappa; partial positive for CD19 and EBER; negative for CD2, CD3, CD5, CD10, CD20, CD56, cyclin D1, ALKp80, HHV-8, MPO, lambda and IgG; and 5% positive for CD30; the Ki-67 positivity rate was 70%." (PMID 41235228, 2025). "Additionally, some covalent CD38 inhibitors have shown enhanced tumor-suppressive effects in isolated Th1/17 hybrid cells, highlighting their potential as CD38-targeted modulators in cancer therapy." (PMID 40529366, 2025). "Compared to APCP, PPCP exhibited significantly lower PD-L1 (an immune checkpoint protein expressed on tumor cells) expression and higher expression levels of CD38 (an immunosuppressive marker), S100A8/A9 (a neutrophil marker), and MPO (myeloperoxidase, a neutrophil marker)." (PMID 40721446, 2025). "Treg, exhaustion and CTLA4/CD38 cGEPs were upregulated in all six tumor types tested (P < 0.05)." (PMID 40903640, 2025). "CD38 is a transmembrane surface protein that is often overexpressed in tumor cells." (PMID 39781471, 2025). "Interestingly, CD38 targeting did not significantly alter the in vivo growth of NRAS;Ink4a lesions, but the combination of anti-CD38 (αCD38)/αPD-1 significantly reduced tumor growth." (PMID 40530504, 2025). "Notably, CD38‐EVsMNs effectively targeted tumour sites with less spleen and lung retention compared to CD38‐EVsi.v and EVsMNs." (PMID 40317915, 2025). "Second, except for CD38, NFKB1, and STAT4, the underlying mechanisms of the other five genes in OC progression and the tumor immune microenvironment remained largely unknown and required further investigation." (PMID 41141246, 2025). "Interestingly, CD38‐negative non‐tumour cells in the co‐culture systems took up significantly fewer CD38‐EVs than EVs." (PMID 40317915, 2025). "CD8+ cells identified in the peripheral blood and tumor of GBM are CD38+ and HLA-DR+42." (PMID 39744577, 2025). "However, the role of CD38 in the metabolic adaptation and regulation of Tregs functionality at the tumor site remains incompletely understood." (PMID 40117361, 2025). "Our results could link this particular structure of CD38 to its potential biological roles in tumor development." (PMID 38545257, 2024).
tumor (continued). "Thus, the on-target off-tumor activity of ISB 2001 was compared to a CD3 × CD38 TCE control and to the CD3 × BCMA TCEs teclistamab and alnuctamab in an HD peripheral blood mononuclear cell (PBMC) assay." (PMID 39261676, 2024). "TE‐1146 precisely delivers lenalidomide to target CD38‐overexpressing tumor cells." (PMID 38477561, 2024). "In T cells, a reduced expression of CD38 was shown to be associated with higher NAD+, enhanced oxidative phosphorylation, higher glutaminolysis, and altered mitochondrial dynamics that improved their tumor control." (PMID 38474166, 2024). "Moreover, anti-CD38 antibodies have been shown to enhance tumor inhibition, and in several clinical trials, have been found to have certain clinical benefits for patients with tumors." (PMID 38404585, 2024). "Pretreatment CD38 density on tumor cells is an important determinant of mAb efficacy." (PMID 40453054, 2024). "Tumor tissue and whole blood were, respectively, analyzed for CD38 expression and patient immune landscapes, which were assessed via cytometry by time-of-flight (CyTOF), multiparameter flow cytometry (MPFC), clonal sequencing, and plasma Epstein-Barr virus (EBV)-DNA level measurements." (PMID 38233570, 2024). "Similarly, CD38+ T cells were established to be an independent prognostic factor for tumor response." (PMID 38404585, 2024). "Moreover, [68Ga]Ga‐AJ206‐PET successfully quantifies CD38 pharmacodynamics in PDXs, revealing increased CD38 expression in the tumor following all‐trans retinoic acid (ATRA) therapy." (PMID 38421139, 2024). "Moreover, compared with anti-CD47 (5F9) and daratumumab, ISB 1442 also mediates increased phagocytosis of T-ALL and AML tumor cells in cell lines with reduced CD38 and CD47 expression." (PMID 38983860, 2024). "Some targets for genetic engineering in NK cells are uniquely expressed in tumor-specific conditions, like Hypoxia-inducible factor 1 in hypoxic environments, while others, like CD38 or CD19, exhibit distinct glycosylation patterns in tumor cells compared to their normal counterparts." (PMID 39199421, 2024). "Tumor cells may inhibit ADCC mediated by anti‐CD38 monoclonal antibodies through the PD‐L1/PD‐1 pathway, and the subsequent upregulation of CD38 expression can inhibit CD8 T cells." (PMID 39492834, 2024). "Thus, the use of targeted therapies such as daratumumab is justified due to the inhibition of tumor growth by binding to the CD38 glycoprotein with high affinity, with the activation of immune-mediated molecular mechanisms." (PMID 38672988, 2024). "In MM, MDS and non-APL AML, the effect of ATRA drug therapy seems to be less obvious, but recent studies have found that ATRA can increase the expression of CD38 and BCMA in tumor cells, which improves the efficacy of daratumumab, CD38-CART, and BCMA-CART, which is encouraging news." (PMID 39027338, 2024). "Daratumumab, a human IgGκ monoclonal antibody targeting CD38 with a direct on-tumor and immunomodulatory mechanism of action, was hypothesized to be a novel therapeutic option for patients with relapsed or refractory (R/R) NKTCL." (PMID 38233570, 2024). "Increased CD38 in TILs (CD38(TILs)) correlated with higher Ki-67 levels in tumor cells." (PMID 39192980, 2024). "We next assessed whether genetic ablation of CD38 in tumor-reactive CD8+ T cells improved their anti-tumor response as well as responsiveness to anti-PD1 therapy." (PMID 38451948, 2024). "Interestingly, we also observed that Pmel-CD38−/− cells retrieved from the tumor site exhibited high TCF1 expression compared to WT Pmel cells." (PMID 38451948, 2024). "Notably, current clinical data are most consistent with pretreatment tumor CD38 antigen density positively correlating with daratumumab depth of response." (PMID 40453054, 2024). "The molecular mechanisms underlying the high expression of CD38 and its promotion of tumor development in tumor cells have not been elucidated." (PMID 38545257, 2024).
tumor (continued). "Because of its distinctive design and diverse modes of action, the CD38/CD47 BsAb has the potential to augment antitumor efficacy in individuals with CD38+ malignancies in comparison to anti-CD38 mAbs by effectively addressing primary and acquired tumor escape mechanisms of resistance." (PMID 38983860, 2024). "Therefore, a rational approach for reducing on-target/off-tumor effects of anti-CD38 CAR-T cells using caspase-9-based suicide gene or affinity optimization has been developed and showed highly suitability for the generation of optimal CARs." (PMID 38783333, 2024). "In addition, clinical data have shown that the elevation of tumor-derived CD38 correlates with poor prognosis in patients with NSCLC." (PMID 38533509, 2024). "This regulation was pivotal in determining the responsiveness to ICB therapy, as tumor-reactive CD8+ T cells with genetic ablation of CD38 (Pmel-CD38−/− T cells) exhibited a robust anti-tumor response to anti-PD1 therapy; however, this effect was abrogated upon Tcf7 knockdown." (PMID 38451948, 2024). "Among all patients and the subgroup of patients treated with PD-1 inhibitors, CD8+CD28+ T cells and NK cells were identified as the common independent prognostic factors for PFS and OS, whereas CD8+CD38+ T cells were common independent prognostic factors for tumor response." (PMID 38404585, 2024). "Next, we investigated whether CD38 blockade enhanced the anti-tumor immune effect of anti-PD-L1 antibody in vivo." (PMID 38533509, 2024). "Pharmacologic manipulation of CD38 density on tumor cells may ultimately be most fruitful before treatment rather than in the context of daratumumab resistance." (PMID 40453054, 2024). "Additionally, a Combinatorial Cellular Library of CD38 CARs enables the enrichment of specific CD38 subgroups through negative screening with normal tissue cells and positive screening with tumor cells, revealing the highest affinity CAR structure designs." (PMID 39538305, 2024). "This is the first study investigating the role of CD38 in anti-tumor immunity of SCLC." (PMID 38533509, 2024). "Because CD20+ B cells and CD4+ CD38+ T cells promote cytotoxic T cells for killing tumor cells, the observed distribution pattern indicates that FOXP3+ Tregs and CD66+ neutrophils might synergistically attenuate this process." (PMID 38674427, 2024). "In this context, an enhanced CD38- and CD47-targeted therapeutic approach that can promote innate immune cell-induced tumor killing potential and overcome anti-CD38 antibody resistance mechanisms may be effective in treating hematologic malignancies." (PMID 38983860, 2024). "In vitro, anti-CD38 antibodies induced the lysis of CD38+ tumor cells through CDC, ADCP, and ADCC." (PMID 38983860, 2024). "The results of the flow cytometry analysis showed that compared to IMM01 (SIRPα Fc fusion protein), all CD38/CD47 BsAbs had a greater ability to bind to CD38+ tumor cell lines in a concentration-dependent manner, and the binding ability of 35G5 and 12C10 was greater than that of the other BsAbs." (PMID 38983860, 2024). "RNA-seq analysis of YFP+ tumor cells sorted from s.c. implanted tumors revealed a decrease in transcript counts for genes encoding 3 adenosine-synthesizing enzymes, CD73, CD38, and CD203a, and an increase in CD39 transcript counts, in Ptges-KO and Ptger4-KO tumors." (PMID 39298269, 2024). "These CD38/CD47 BsAbs could selectively block the interaction between CD47 and SIRPα on CD38+/CD47+ tumor cells and induce tumor cell death in vitro and in vivo." (PMID 38983860, 2024). "In HCC, a high frequency of CD38+PD-1+CD8+ T cells is associated with high histopathological grades (III and IV), thereby indicating that CD38, a T-cell co-exhaustion marker, is linked to tumor aggressiveness." (PMID 38404585, 2024).
tumor (continued). "By having the ability to bind BCMA and CD38 simultaneously, TCE’s avidity to bind to the target tumor is advantageous and was associated with low on-target, off-tumor activity compared with the combination of the CD38-specific and BCMA-specific TCEs constructed with the same binding domains." (PMID 39364307, 2024). "ISB 1442 consists of two anti-CD38 arms targeting two distinct epitopes that preferentially drive binding to tumor cells and enable avidity-induced blocking of proximal CD47 receptors on the same cell while preventing on-target off-tumor binding on healthy cells." (PMID 38448430, 2024). "However, ISB 1442 induced strong killing of tumor cells from patients treated with anti-CD38 therapies, whereas daratumumab induced only a low level of killing." (PMID 38448430, 2024). "In summary, although daratumumab induces on-tumor activity, through several CD38 immune-mediated and CD38-modulating actions, and induces immunomodulatory effects in patients with MM, its effects on CD38-expressing R/R NKTCL tumor cells as observed in the NKT2001 study were suboptimal." (PMID 38233570, 2024). "Whether NAD+ase activity inhibition using an anti-CD38 immunotherapy is beneficial or harmful for tumor cells is still unclear, with studies suggesting a cell-dependent outcome." (PMID 36830052, 2023). "In addition to the favourable prognostic value of CD20+ B cell infiltration, the role of tumour-infiltrating plasma cells, defined immunohistochemically as CD38+ or CD138+ cells in most studies, has been explored." (PMID 36831506, 2023). "In the tumor microenvironment, CD38 expression on immune cells may also contribute to consume extracellular NAD+." (PMID 37261423, 2023). "The clinical development of next‐generation anti‐CD38 antibodies, as well as new modalities targeting this tumor antigen, may provide more effective treatment options for improved outcomes in the advanced lymphoid malignancy space." (PMID 36251503, 2023). "Studies of CAR‐T cells targeting CD38 have demonstrated their anti‐tumor efficacy." (PMID 37039305, 2023). "The CD38-NbCAR-T cells exposed to CD38+ tumors could proliferate effectively, kill the target cells, and reduce the tumor size in an in vivo evaluation." (PMID 36761751, 2023). "The data showed that CD38 was highly expressed (7/10 positive) in NKTCL tumour tissues." (PMID 37649020, 2023). "In addition to using the CD34+/CD38 phenotype to identify CSC-like cells, we also examined the effect of NK3.3EVs on the expression of genes associated with CSC-like cells and tumor progression." (PMID 38201518, 2023). "For example, fusion of IFN-α to anti-CD38 mAb increased cytokine specificity to CD38+ tumor cells 10,000-fold, meaning that patients might be safely treated with high doses of fusion protein." (PMID 36839658, 2023). "Moreover, CD38 has been found as a tumor antigen and as a target for tumor therapy in many different tumor cells, e.g., lymphoma, myeloma, and in solid tumors." (PMID 36831342, 2023). "In addition to the other mechanisms of action that result in tumor cell death or phagocytosis, CD38 has immunomodulatory effects on the BM tumor microenvironment, with multiple pathways for CD38‐mediated T‐cell activation." (PMID 37840445, 2023). "Therefore, these CD38 CAR‐T cells demonstrated potent cytotoxicity against tumor cells in vitro, while CD38KO/KIEF1α CAR‐T cells performed better in terms of cytokine secretion and proliferation than CD38KO/KI CAR‐T cells." (PMID 37485647, 2023). "Optimization of the tumor cell affinity of CAR‐T cells may improve the specificity for CD38 recognizing and reduce side effects." (PMID 37039305, 2023). "However, the understanding of the impact of CD38 on tumor progression remains limited, ambiguous, and controversial." (PMID 36845744, 2023). "Also, anti-CD38 mAbs have been shown to enhance T cell function and suppress Treg cell proliferation in the tumor microenvironment in vivo." (PMID 38116009, 2023).